BDNF (brain derived neurotrophic factor)
Diseases named in the same sentence as BDNF in open-access papers (continued):
Sharing a sentence is not in itself a finding about the gene and the disease.
gallbladder cancer (3 papers, 2013 to 2025). "This study aims to demonstrate the clinical and biological significance of Brain derived neurotrophic factor (BDNF)/Tropomyosin-related kinase B (TrkB) signaling in gallbladder cancer (GBC) through a series of in vitro and in vivo experiments." (PMID 28423707, 2017). "More extensive studies are required to determine the mechanistic roles of BDNF and BMPR1A in the development and progression of gallbladder cancer." (PMID 23531103, 2013). "We suggest that there may be a relationship between BDNF and BMPR1A, but it remains unclear how BDNF and BMPR1A together affect the action of tumors, such as gallbladder cancer." (PMID 23531103, 2013). "However, the expression levels of BDNF and BMPR1A and their clinicopathologic significance in malignant tumors, particularly gallbladder cancer, have not been thoroughly evaluated." (PMID 23531103, 2013).
HIV-1 infection (3 papers, 2014 to 2021). The type species of lentivirus and the etiologic agent of acquired immunodeficiency syndrome (AIDS). "Clinical and experimental research has shown that reduced levels of brain-derived neurotrophic factor (BDNF) may be a risk factor for neurological complications associated with HIV-1 infection." (PMID 24505242, 2014).
internalizing disorder (3 papers, 2014 to 2024). A type of mental or behavioral disorder, typically in children and young adults, with symptoms including depression, anxiety and withdrawal. "In fact, some genetic factors putatively influencing the individual variations in neuroticism substantially overlap with the candidate genes identified with internalizing disorders (e.g., gene encoding for the serotonin transporter, the brain-derived neurotrophic factor [BDNF])." (PMID 38672016, 2024).
leukemia (3 papers, 2016 to 2025). A malignant (clonal) hematologic disorder, involving hematopoietic stem cells and characterized by the presence of primitive or atypical myeloid or lymphoid cells in the bone marrow and the blood. "A study by our research group showed that decreased BDNF levels at leukemia diagnosis in children are associated with a worse prognosis and active disease." (PMID 40427122, 2025). "This suggests a severe influence of BDNF in B-ALL formation, since leukemia causes are intrinsically related to cell development stages." (PMID 40427122, 2025). "NTRK2 and its ligand BDNF have been shown to be co-expressed in acute leukemia blasts, and this negatively correlates with survival of leukemia patients." (PMID 27672444, 2016). "In leukemia, specifically, BDNF was reported to promote B chronic lymphocytic leukemia cells." (PMID 40427122, 2025). "Surprisingly, pro-BDNF follows the same pattern as BDNF and is reduced in childhood leukemia samples, discarding the hypothesis of a derangement in the conversion from pro-NTs to mature NTs." (PMID 40427122, 2025). "Furthermore, the reduction effect in patients’ leukemic cells by BDNF treatment suggests a possible influence of BDNF in response to leukemia therapy, but further studies are required to explore this therapeutic potential." (PMID 40427122, 2025). "Because BDNF stimulation promoted formation of the NTSR2–TrkB complex in leukemia cells, we analyzed both BDNF expression in B-CLL and circulating BDNF in plasma derived from B-CLL patients or HDs." (PMID 29059151, 2018). "Mice with bone marrow transduced with both NTRK2 and BDNF developed AML and T-ALL, suggesting a role of NTRK2 in leukemia pathogenesis." (PMID 27672444, 2016).
liver cancer (3 papers, 2022 to 2025). An epithelial or non-epithelial malignant neoplasm that arises from the liver. "In another study with liver cancer patients, the rs6265 SNP of BDNF was also shown to be positively associated with PTSD risk, where carriers of the rare allele of the SNP were about three times more likely to have PTSD." (PMID 35528795, 2022). "Over the past decades, BDNF also has been found to take part in cancer development, including brain, breast, urinary, gastric, colon, pancreas, and liver cancer." (PMID 40075616, 2025).
methamphetamine dependence (3 papers, 2017 to 2024). A drug dependence that is a psychological dependency on the regular use of methamphetamine. "In this line, protein that interact with C-kinase-1 (PICK1) and brain-derived neurotrophic factor (BDNF) genes are linked to methamphetamine dependence (substance use disorder)." (PMID 33499851, 2021). "Therefore, we aimed to investigate the association between PICK1 and BDNF main SNPs and methamphetamine dependence (substance use disorder (SUD)) in a cohort of Iranian individuals." (PMID 33499851, 2021). "Thus, in a case–control study, we investigated the association between polymorphisms of PICK1 and BDNF genes and methamphetamine dependence in an Iranian population." (PMID 33499851, 2021).
microcephaly (3 papers, 2020 to 2023). A congenital or acquired developmental disorder in which the circumference of the head is smaller than normal for the person's age and sex. "In particular, defects in the BDNF/TrkB signaling pathway might constitute a common molecular underpinning of neurodevelopmental disorders associated with postnatal microcephaly." (PMID 36845425, 2023). "However, the extent to which the different histone methyltransferases that have been associated with postnatal microcephaly could modulate brain size by modulating the BDNF/TrkB signaling pathway is underexplored." (PMID 36845425, 2023). "In the absence of a clear role for the inflammation response in the presentation of microcephaly, the amount of placental BDNF, a factor described as a determinant for fetal brain development, was evaluated." (PMID 32983175, 2020). "The placentae of patients infected with ZIKV, especially from the group that presented infants with microcephaly, showed a decrease in BDNF expression, which suggests that BDNF levels in the placenta could serve as predictive marker for the extent of damage during fetal brain development." (PMID 32983175, 2020). "Finally, we evaluated the expression of brain derived neurotrophic factor (BDNF), an essential factor for fetal brain development, which may be one of the determinant proteins that contribute to the severity of microcephaly due to vertical transmission in ZIKV infection." (PMID 32983175, 2020).
morbid obesity (3 papers, 2011 to 2021). An excess of body weight, normally defined as an individual with a body mass index greater than 35 or a body weight greater than one hundred percent of ideal body weight. "Additionally, besides the important role of BDNF in synaptic plasticity, this neurotrophin also regulates feeding and weight, with evidence showing that a hypomorphic or loss-of-function allele of the TrkB-FL gene triggers excessive appetite, reduced energy expenditure and morbid obesity in mice." (PMID 34940136, 2021). "The strength of our study is that we compared the circulating BDNF/FGF21, clinical characteristics, and biochemical parameters in patients with morbid obesity before and 6 months after LSG." (PMID 32210348, 2020). "The circulating level of FGF21 was higher in the diabetic patients with morbid obesity than the non-diabetic subjects, while the level of BDNF was similar between the two groups." (PMID 32210348, 2020).
muscle atrophy (3 papers, 2012 to 2025). The loss of muscle tissue due to inactivity or disease. "In addition, future studies should be carried out in patients with muscle atrophy to analyze whether there is a correlation between IGF-1, other pro-hypertrophic markers, BDNF levels, an increase in muscle circumference, and an improvement in the subjects’ mood or cognitive processes." (PMID 39329748, 2024).
neuronal tumor (3 papers, 2014 to 2024). Neuronal brain tumors are an uncommon group of central nervous system tumors that arise from cells with neuronal differentiation. "Although both TrkB and p75NTR involved in proliferation, differentiation, survival and apoptosis of neuronal and non-neuronal tumors, p75NTR preferentially acts as an interacting partner of TrkB, modulates TrkB activation by BDNF, and influences prosurvival effect by BDNF/TrkB signaling." (PMID 24801982, 2014).
neutropenia (3 papers, 2020 to 2023). A decrease in the number of neutrophils found in the blood. "For example, an increased probability of neutropenia with WT alleles of BDNF rs6265 and hence increased BDNF secretion was not expected as BDNF has previously been shown to promote immune recovery after radiation treatment in a pre-clinical model." (PMID 37162533, 2023). "Since agonism of BDNF-TrkB signaling supports regeneration of both the bone marrow and thymus following radiation injury, these data would support the therapeutic use of BDNF or 7,8-DHF for the treatment of radiation-induced neutropenia and lymphocytopenia." (PMID 34695155, 2021).
non-proliferative diabetic retinopathy (3 papers, 2020 to 2024). Early stage diabetic retinopathy, characterized by the absence of neovascularisation of the retina. "The mean BDNF was found to be minimum in the moderate non-proliferative diabetic retinopathy (NPDR) group (1517.02 ± 513.74), whereas it was found to be maximum in the severe NPDR group (1719.76 ± 308.50)." (PMID 39712817, 2024). "Indeed, diabetic mice from our experimental setting showed decreased BDNF retinal levels, confirming the previous results reported in the retina of diabetic rodents and in the serum of patients with non-proliferative diabetic retinopathy (NPDR)." (PMID 36077579, 2022).
opioid use disorder (3 papers, 2015 to 2024). A substance-related disorder that involves the recurring use of opioids despite negative consequences. "BDNF 196G>A (rs6265) and DRD2-241A>G (rs1799978) genetic variants were examined in patients with opioid use disorder who were recruited from methadone treatment clinics across Southern Ontario, Canada." (PMID 26437921, 2015). "The aim of this study was to investigate the effect of brain-derived neurotrophic factor (BDNF) and dopamine receptor D2 (DRD2) polymorphisms on continued opioid use among patients on methadone treatment for opioid use disorder." (PMID 26437921, 2015). "They performed a haplotype analysis of 30 SNPs in the BDNF coding region, including rs6265, in a sample of 91 Caucasian individuals receiving methadone treatment for opioid use disorder." (PMID 26437921, 2015). "Considering that increasing evidence indicates that BDNF may serve a neuroprotective role in opioid use disorders, this might suggest a neuroprotective mechanism in male brains during chronic opioid use." (PMID 38535622, 2024). "Variation in addiction-related genes (such as BDNF and DRD2) due to polymorphisms in the genetic sequence may confer susceptibility to continued opioid use while on methadone treatment for opioid use disorder." (PMID 26437921, 2015). "Located on chromosome 11p13-15, BDNF has been identified as a strong candidate gene in multiple psychiatric and substance use disorders, including opioid use disorder, as well as for certain addictive behaviors such as drug seeking, impulsivity, polysubstance use, and cigarette smoking." (PMID 26437921, 2015).
osteosclerosis (3 papers, 2017 to 2023). Abnormally high bone density. "Twenty-eight days after surgery, μCT analysis indicated that exogenous BDNF significantly accelerated the regeneration of the cortex and induced osteosclerosis surrounding the bones as indicated by arrows." (PMID 28072837, 2017). "Exogenous BDNF also promoted osteosclerosis after cortical osteotomy in our in vivo experiment." (PMID 28072837, 2017).
ovarian dysfunction (3 papers, 2016 to 2024). The inability of the ovaries to function. "This opens up new possibilities for developing biomedical procedures for the BDNF-triggered stimulation of GC-based regenerative and reconstructive medicine in female patients exhibiting ovarian dysfunctions." (PMID 38397033, 2024). "We infer that aerobic exercise increases BDNF, plays an anti-apoptotic role, and corrects ovarian dysfunction." (PMID 36233452, 2022). "Ovarian failure induced by 4-vinylcyclohexene diepoxide treatment dramatically reduced BDNF and TH expression in gWAT, eliminated induction of UCP1 by CL, and reduced tissue metabolic rate." (PMID 27990249, 2016). "Importantly, BDNF expression was upregulated by estrogen treatment in vitro, and VCD-induced ovarian failure reduced BDNF expression." (PMID 27990249, 2016).
phobia (3 papers, 2013 to 2023). "A systematic search was conducted involving all pairwise combinations of Acne vulgaris and these items: ‘‘quality of life’’, ‘‘brain-derived neurotrophic factor’’, ‘‘BDNF’’, ‘‘depress*’’, ‘‘anx*’’, ‘‘psychiat*’’, ‘‘psycho*’’, ‘‘phobia’’, ‘‘stress’’, ‘‘suicide’’, ‘‘loneliness’’, ‘‘self-esteem”." (PMID 36751189, 2023).
prediabetes (3 papers, 2021 to 2025). "However, it seems a bit more complex since prediabetes is associated with higher BDNF concentrations." (PMID 34992516, 2021). "Short‐term exercise training lowered fasting pro‐BDNF and increased glucose‐stimulated total Akt derived from neuronal extracellular vesicles (nEVs) in relation to peripheral insulin sensitivity among older adults with prediabetes." (PMID 39421964, 2025). "We tested the hypothesis that short‐term exercise would raise neuronal insulin signaling and pro‐BDNF in neuronal extracellular vesicles (nEVs) in prediabetes." (PMID 39421964, 2025). "However, no study was found that investigated the relationship between cognition and BDNF in prediabetes patients." (PMID 36936159, 2023). "However, to date, no studies have examined whether exercise may impact nEV cargo as it relates to insulin signaling mediators and pro‐BDNF in older adults with prediabetes." (PMID 39421964, 2025).
Pruritus (3 papers, 2021 to 2022). Pruritus is an itch or a sensation that makes a person want to scratch. "Furthermore, correlations between the concentration of NT-4 or BDNF and the severity of pruritus were determined." (PMID 36362520, 2022). "In addition, skin disruption in HDM-treated Grhl3PAR/+ mice also upregulated pruritus and inflammatory-related gene expression in sensory neurons, including TSLPR, IL-31 receptor α, and brain-derived neurotrophic factor (BDNF)." (PMID 34281281, 2021).
psychosomatic disorders (3 papers, 2025). "Previous researches have indicated links between BDNF with appetite, energy metabolism, and a range of psychosomatic disorders." (PMID 40513379, 2025). "This review first outlines how epigenetic dysregulation contributes to psychosomatic disorders through altered expression of genes such as GRM2, TRPA1, SLC6A4, NR3C1, leptin, BDNF, NAT15, HDAC4, PRKCA, RTN1, PRKG1, and HDAC7." (PMID 41439979, 2025). "BDNF, NfL and GFAP concentrations in serum and CSF were assessed in 106 treatment na﻿ïve patients with MS (pwMS) as well as 73 patients with other inflammatory/non-inflammatory neurological or somatoform disorders using a single molecule array HD-1 analyser." (PMID 39812717, 2025).
R6 (3 papers, 2008 to 2024). "A recent study using the R6/1 HD mice model showed that the BDNF mRNA levels of striatal in the HD standard housed (SH) mice were 60% lower than wild-type (WT) SH mice." (PMID 36389059, 2022). "We have shown that environmental enrichment can rescue the deficit of mature BDNF protein in the striatum of R6/1 HD mice." (PMID 18380890, 2008).
renal carcinoma (3 papers, 2009 to 2016). A carcinoma arising from the epithelium of the renal parenchyma or the renal pelvis. "Taken together, these data suggested that p75NTR and pro-BDNF are expressed in our experimental model of renal carcinoma-derived cell lines." (PMID 27120782, 2016). "Next, the function of pro-BDNF as prosurvival factor through p75NTR was studied in renal carcinoma cell lines." (PMID 27120782, 2016). "BDNF/TrkB should be considered in future studies to assess its potential role as a biomarker and therapeutical target in renal carcinoma." (PMID 19904265, 2009). "For example, in PC12 cells, RanBPM modulates BDNF-induced neuronal morphogenesis by regulating TrkB activation of MAPK and Akt, and, in human renal carcinoma cells, RanBPM enhances HGF-induced cell migration by interacting with Met and promoting GTP-Ras association and Erk phosphorylation." (PMID 27835883, 2016). "Although the involvement of BDNF and TrkB remains unknown in renal carcinoma, one study has reported that sera from non-responder patients to Sunitinib (a tyrosine kinase inhibitor with anti-angiogenic activity) contained high levels of BDNF." (PMID 27120782, 2016).
renal dysfunction (3 papers, 2022 to 2023). "Changes in brain structure and neurotrophic factors account for impaired cognitive functions in renal dysfunction, e.g. decrease in brain-derived neurotrophic factor (BDNF) expression." (PMID 36469209, 2023). "Patients in the current study represent latter stages of CKD and have KF, therefore it may be possible that with worsening renal dysfunction the sex difference in levels of BDNF is lost." (PMID 35292710, 2022). "Moreover, the behavioural changes might be related to changes in hippocampal BDNF and GFAP expression, which are common in renal dysfunction." (PMID 36420617, 2023).
restless legs syndrome (3 papers, 2021 to 2024). A condition that occurs while resting or lying in bed; it is characterized by an irresistible urgency to move the legs to obtain relief from a strange and uncomfortable sensation in the legs. "Decreased serum BDNF levels may be involved in the pathophysiology of restless legs syndrome (RLS) in Parkinson’s disease." (PMID 35743271, 2022). "Recent studies have shown that rotigotine, as a non-ergot dopamine receptor agonist, is clinically used in the treatment of restless legs syndrome, which may play its role by improving the function of BDNF in the brain." (PMID 34764928, 2021). "A cross‐sectional study included 53 PD patients with restless leg syndrome, 196 PD patients without restless leg syndrome and 326 matched controls showed that BDNF serum level was reduced in PD patients with restless leg syndrome." (PMID 38752280, 2024).